SET (SET nuclear proto-oncogene)
Diseases named in the same sentence as SET in open-access papers (continued):
Sharing a sentence is not in itself a finding about the gene and the disease.
breast carcinoma (18 papers, 2015 to 2024). "An analysis of the KM‐plotter database revealed SET expression to be associated with worse ER‐α‐positive breast cancer patient OS, RFS, and DMFS following TAM treatment." (PMID 35843886, 2022). "In the present study, we found that high expression of SET or CIP2A was associated with worse RFS in patients with ER-positive primary breast cancer receiving the adjuvant tamoxifen treatment." (PMID 30154367, 2018). "SET deficiency significantly impaired the tumorigenic potential of breast cancer cell lines." (PMID 29749127, 2018). "Among the fifteen best-ranked ferroptosis genes in breast cancer, eleven harbored some association with “extracellular matrix remodeling” literature in the PUBMED database, especially TNF, SET, and IL6, found to be highly cited in this specific literature." (PMID 37681908, 2023). "In breast cancer, the SET protein was found to be overexpressed, and its knockdown decreased tumorigenesis." (PMID 32752177, 2020). "Given that PP2A maintains the activation of some oncogenic survival signals, SET is therefore an attractive and powerful therapeutic target for breast cancer therapy." (PMID 32752177, 2020). "For example, over-expression of SET (SET nuclear proto-oncogene), defined as a tumor cell-specific signature, has been demonstrated in 50–60% of breast cancer cases." (PMID 31100099, 2019). "We next examined the role of SET in tamoxifen-treated breast cancer cells by ectopic overexpression of SET in the MCF7 cells followed by the tamoxifen treatment." (PMID 30154367, 2018). "Various studies have shown a preferential overexpression of SET in chronic myelogenous leukemia, head and neck squamous cell carcinoma, non-small cell lung cancer, colorectal cancer, and breast cancer." (PMID 30154367, 2018). "The results disclosed that breast cancer patients with SET gene overexpression had worse RFS compared with those with low SET gene expression (p < 0.001, HR = 1.88, CI = 1.37–2.58)." (PMID 30154367, 2018). "Consistent with our data, SET KD is known to suppress the proliferation of human breast cancer cells." (PMID 28655918, 2017). "In human breast cancer, increased SET protein level has been reported to lead to c-Myc stabilization." (PMID 28655918, 2017). "In human breast cancer cell lines, SET knockdown (KD) suppressed cell proliferation and anchorage-independent cell growth." (PMID 28655918, 2017). "In this study, SET protein levels were found to be elevated in advanced-stage of canine mammary tumor tissues." (PMID 28655918, 2017). "Although further investigation is required to confirm this, our findings suggest that PP2A activation by SET KD suppressed mTORC1/p70S6K, β-catenin, and NFκB signaling in the canine mammary tumor cells." (PMID 28655918, 2017). "Knockdown of SET expression in a canine mammary tumor cell line CIP-m led to increased PP2A activity and decreased cell proliferation, colony formation, and in vivo tumor growth." (PMID 28655918, 2017). "In the present study, the PP2A inhibitory protein SET/I2PP2A was shown to be highly upregulated in canine mammary tumor tissues." (PMID 28655918, 2017). "SET protein levels were found to be significantly elevated in stage II-V mammary tumor tissues compared with stage I mammary tumor tissues." (PMID 28655918, 2017). "Consistent with our previous finding, SET KD in the present study resulted in decreased phosphorylated p70S6K in canine mammary tumor cells." (PMID 28655918, 2017). "These cell lines were chosen based on their CIP2A and SET overexpression levels and because they represent aggressive breast cancer phenotypes (MDA-MB-231: triple negative; BT-474: HER-2)." (PMID 25726524, 2015). "In concordance with our findings, a recent work has shown that both CIP2A and SET are frequently co-overexpressed with c-MYC in breast cancer cell lines." (PMID 25726524, 2015).
breast carcinoma (continued). "In contrast, we proved that extended inhibition of CIP2A expression, SET-induced PP2A inhibition and PP2A-phosphorylation by FTY720 treatment caused a deeply antitumoral effect in breast cancer cells." (PMID 25726524, 2015). "In addition, PP2A directly targets pAKT, and endogenous PP2A inhibitors such as SET havebeen described to be altered in breast cancer and involved in pAKT regulation." (PMID 35329936, 2022). "Elevated SET protein levels are observed in various human tumors, including colorectal cancer, gastric cancer, pancreatic cancer, breast cancer, non-small cell lung cancer, and acute myeloid leukemia, and SET levels are correlated with poor prognosis and drug-resistance." (PMID 31557212, 2019). "Furthermore, the public database Kaplan–Meier Plotter also disclosed that higher SET gene expression, which encodes oncoprotein SET, was associated with poor RFS with primary breast cancer receiving the adjuvant tamoxifen treatment." (PMID 30154367, 2018). "Although SET is frequently overexpressed in human breast cancer, it was previously unknown whether SET protein levels are enhanced in canine mammary tumor tissues." (PMID 28655918, 2017). "Next, the SET protein levels in canine mammary tumor cell lines, CIP-p and CIP-m, were examined." (PMID 28655918, 2017). "Moreover, future studies evaluating PP2A phosphorylation after knock-down of SET or CIP2A are warranted to assess their relevance in regulating PP2A activity in breast cancer." (PMID 25726524, 2015). "Therefore, it remains necessary to analyze whether SET is proteolyzed in breast cancer before concluding that SETBP1 could contribute to PP2A inhibition in this disease." (PMID 25726524, 2015). "SET KD and SET inhibitor OP449 suppressed mTORC1 signaling in canine osteosarcoma and human breast cancer cell lines." (PMID 38141761, 2024). "The overexpression of SET suppressed tamoxifen-induced anti-cancer effects and upregulated estrogen receptor element (ERE)-dependent ER signaling transactivation, indicating that SET may be associated with the failure of tamoxifen treatment in ER-positive breast cancer MCF-7 cells." (PMID 37097392, 2023). "Here, we analyze these aspects in the context of breast cancer, targeting PP2A/SET interaction, using both in silico and in vivo approaches." (PMID 37111665, 2023). "PP2A hyperphosphorylation, as well as upregulation of the endogenous PP2A inhibitors such as SET, has been reported as main molecular mechanisms of PP2A inhibition in many tumors including breast cancer." (PMID 33809005, 2021). "We and others have shown that SET and CIP2A, two oncogenic inhibitors of PP2A, are overexpressed in various cancers, including hematopoietic malignancies and breast cancer." (PMID 27705940, 2016). "To investigate the prevalence and clinical significance of PP2A inhibition, we quantified SET, CIP2A and phosphorylated PP2A (p-PP2A) expression in a cohort of 230 patients with early breast cancer mainly treated with anthracyclin-based adjuvant chemotherapy." (PMID 25726524, 2015). "To determine its clinical relevance, we quantified SET, CIP2A and PP2A phosphorylation in a series of 230 breast cancer patients, observing that PP2A inhibition is a recurrent molecular event that determines shorter overall and event-free survival." (PMID 25726524, 2015). "Several studies showed that SET was up-regulated in acute myeloid leukemia, head and neck squamous cell carcinoma (HNSCC), colorectal cancer, and breast cancer." (PMID 25945834, 2015). "We report here that PP2A inhibition is a frequent event in breast cancer and identified PP2A hyperphosphorylation together with SET and CIP2A overexpression as molecular mechanisms that cooperate to inactivate this phosphatase." (PMID 25726524, 2015). "Here, we show that PP2A inhibition is a common event in breast cancer and identified PP2A phosphorylation and deregulation SET and CIP2A as molecular contributing mechanisms to inactivate PP2A." (PMID 25726524, 2015).
breast carcinoma (continued). "In this study, we show that PP2A is commonly inactivated in breast cancer and identify that CIP2A and SET overexpression together with PP2A hyperphosphorylation are key contributing mechanisms to inhibit PP2A in this disease." (PMID 25726524, 2015). "In concordance with the results showed by the PP2A activity assays, we found PP2A hyperphosphorylated together with SET and CIP2A markedly overexpressed in all the breast cancer cell lines analyzed." (PMID 25726524, 2015). "SET, CIP2A, and pS62-MYC proteins are commonly overexpressed in human breast cancers." (PMID 37097392, 2023). "In human breast cancer cells, SET KD has been shown to decrease c-Myc protein levels by enhancing the dephosphorylation of c-Myc Ser6216, while in this study SET KD did not alter c-Myc protein levels in canine mammary tumor cells." (PMID 28655918, 2017). "Moreover, SET and CIP2A were found to be endogenous inhibitors of PP2A, and SET, CIP2A, and pS62-MYC proteins are commonly overexpressed in human breast cancers." (PMID 28124725, 2017). "SET KD was furthermore shown to enhance PP2A activity; to inhibit mTORC1/p70S6K, β-catenin, and NFκB signaling; and to suppress the tumorigenic characteristics of a canine mammary tumor cell line." (PMID 28655918, 2017). "Similarly, SET overexpression in patients with several solid tumor, including colorectal cancer, head and neck squamous cell carcinoma (HNSCC), colorectal cancer, and breast cancer, shows promising therapeutic implications and determines poor clinical outcome." (PMID 25945834, 2015). "Our data showed that SET overexpression enhanced ERE-mediated ER activity, suggesting that SET could possibly interfere with the ER signaling pathways and contribute to tamoxifen resistance in breast cancer, at least, in part, via the inhibition of PP2A activity." (PMID 30154367, 2018). "However, the role of SET in canine mammary tumor has not yet been studied." (PMID 28655918, 2017). "Thus, we observed a reduced PP2A activity in all the five breast cancer cell lines analyzed, identifying PP2A hyperphosphorylation and SET and CIP2A overexpression in all cases, which prompted us to hypothesize that these could be relevant contributing mechanisms to inhibit PP2A in breast cancer." (PMID 25726524, 2015). "Moreover, the authors studied publically available datasets (cBioPortal) and reported that PP2A activation status could be deregulated in more than 50% of basal breast cancer tumors due to alterations affecting PP2A subunits or deregulation of endogenous PP2A inhibitors such as SETBP1, SET or CIP2A." (PMID 25726524, 2015).
acute myeloid leukemia (17 papers, 2009 to 2024). Acute myeloid leukemia (AML) is a group of neoplasms arising from precursor cells committed to the myeloid cell-line differentiation. "In acute myeloid leukemia (AML), overexpression of protein phosphatase 2A inactivator SET is associated with a poor prognosis." (PMID 39201306, 2024). "Overexpression of SET, which in many cases is known to be a potent PP2A inhibitor is associated with poor prognosis in Acute Myeloid Leukaemia (AML)." (PMID 25867001, 2015). "Regarding the molecular mechanisms responsible for SET deregulation, the transcription factor ecotropic virus integration site-1 (EVI-1) has been reported to promote SET expression in acute myeloid leukemia, and miR-199b has been found to be negatively regulate SET in choriocarcinoma." (PMID 30871013, 2019). "Because the efficacy of peptide SET inhibitor OP449 was only confirmed in mice xenografted with drug-sensitive human acute myeloid leukemia HL-60 cells, ponatinib, the only therapeutic agent for T315I mutation of CML patients, was chosen as a positive control for the comparison of in vivo efficacy." (PMID 25900240, 2015). "SET is an oncoprotein—also known as I2PP2A or TAF1—and was identified as a SET‐CAN fusion protein in acute non‐lymphocytic leukemia, produced by the deletion of chromosome 9." (PMID 37489294, 2023). "However, the fact that SET is overexpressed in myeloid leukemias, including chronic myeloid leukemia (CML) and acute myeloid leukemia (AML), prompted us to examine the physiological function of SET in myeloid cells, particularly in TAMs." (PMID 36224346, 2022). "The SET-CAN fusion gene has been found in the T-cell acute lymphoblastic leukemia (T-ALL) cell line LOUCY and acute myeloid leukemia (AML) line MEGAL." (PMID 35905214, 2022). "Odero MD and colleagues had showed that PP2A inactivation is a recurrent event in acute myeloid leukemia (AML) and that overexpression of SET (I2PP2A) is a poor prognostic factor in this disease." (PMID 25015035, 2014). "Likewise, SET protein levels were also found to be high in leukemia, including chronic myeloid leukemia (CML) and acute myeloid leukemia (AML) and lymphoma." (PMID 34244560, 2021).
pancreatic cancer (13 papers, 2013 to 2025). "High SET protein levels are also associated with poor prognosis of metastatic colon cancer, non-small-cell lung cancer, pancreatic cancer, gastric cancer, liver cancer, CML, AML, and lymphoma." (PMID 34244560, 2021). "In this study, we demonstrate SET isoform 2 as the predominantly overexpressed form of SET in pancreatic cancer and that it triggers N-cadherin expression for acquisition of EMT characteristics possibly through the Rac-1/JNK/c-jun pathway." (PMID 28978088, 2017). "Among the two major isoforms of SET (isoform 1 and isoform 2), higher protein levels of SET isoform 2 were identified in aggressive pancreatic cancer cell lines." (PMID 28978088, 2017). "Since SET Isoform 2 was more consistently overexpressed in pancreatic cancers and SET Isoform-2 induced more prominent EMT-related phenotypic changes in PANC-1 as compared with SET Isoform 1, we focused only on SET Isoform 2 for further mechanistic studies." (PMID 28978088, 2017). "Similar to Western blotting results, Real-time PCR analyses showed SET isoform-2 overexpressed in the majority of pancreatic cancer cell lines tested." (PMID 28978088, 2017). "Consistent with pancreatic cancer cell lines, total SET and SET isoform 2 were significantly overexpressed in PDAC samples and not in other pancreatic tumor subtypes compared with normal pancreatic tissues." (PMID 28978088, 2017). "Western Blotting data identify that SET isoform 2, similar to total SET, is overexpressed in all pancreatic cancer cell lines (except AsPC-1) whereas SET isoform 1 was majorly increased only in L3.6pl and Capan-1." (PMID 28978088, 2017). "The results showed total SET protein increased in all pancreatic cancer cell lines tested (except AsPC-1) compared with normal HPDE." (PMID 28978088, 2017). "SET itself, as judged by Western blotting, was found to be overexpressed in most of the pancreatic cancer cell lines when compared with HPDE." (PMID 23335963, 2013). "Our data showed high expression levels of SET oncoprotein in many of the pancreatic cancer cell lines; to our knowledge this is the first report demonstrating SET overexpression in pancreatic cancer." (PMID 23335963, 2013). "Indeed, in human pancreatic cancers with KRAS mutations, SET/CIP2A overexpression correlates with the increased expression of IEGs, resulting in poor clinical outcomes." (PMID 36463234, 2022). "Interestingly, we also found SET knockdown to increase the epithelial features of pancreatic cancer cells by promoting compact colony morphology with smooth colony edges and increased cell-to-cell contacts." (PMID 28978088, 2017). "To investigate the possible differential effects of different SET Isoforms on EMT and growth in pancreatic cancer, we transfected SET Isoform 1 overexpressing plasmid tagged with FLAG (SET-FLAG) in PANC-1 and investigated phenotypic growth and morphological changes as before." (PMID 28978088, 2017). "We earlier reported SET knockdown to reduce growth and colony formation of pancreatic cancer cells." (PMID 28978088, 2017). "Since targeting SET at the cell surface is pharmacologically tractable, further studies in this direction are likely to identify new opportunities for intervening pancreatic tumor progression." (PMID 28978088, 2017). "Whether SET increases Rac1 activity to increase migratory capabilities in pancreatic cancer remains unknown; however, it is likely that both SET overexpression and Rac1-induced SET recruitment to the cell surface can concomitantly amplify migratory signals during EMT." (PMID 28978088, 2017). "Knockdown of SET increased c-MYC degradation and it decreased the tumorigenic potential of pancreatic cancer cell lines both in vitro and in vivo." (PMID 36345878, 2022).
pancreatic cancer (continued). "Furthermore, scatter plot analyses showed significant positive correlations of SET/CIP2A expression with the expression levels of the IEGs (TRIB1, SPRY4, CTGF) and with those of growth-promoting genes (cyclin D1, E2, and PCNA) in KRAS-mutated pancreatic cancers." (PMID 36463234, 2022). "To understand the role of SET in EMT, we identified total SET expression in a panel of pancreatic cancer cell lines." (PMID 28978088, 2017). "Thus, our data lends further credence to these findings and provide a new molecular link between SET, JNK, and N-cadherin for activation of EMT in pancreatic cancer cells." (PMID 28978088, 2017). "Taken together, these findings illustrate a novel role for SET in EMT and suggest that SET oncoprotein may be utilized as a therapeutic target to minimize EMT and metastasis in a subset of pancreatic cancer patients." (PMID 28978088, 2017). "In this study, we investigated the putative roles of SET in EMT and pancreatic tumor progression." (PMID 28978088, 2017). "Our data is consistent with a recent report that sensitivity to FTY720 is not correlated with SET expression level across cancer cell lines and that FTY720 remains effective against pancreatic cancer cells after SET is knocked out." (PMID 40588551, 2025).